RNU6-1181P (RNA, U6 small nuclear 1181, pseudogene)
Gene: Small nuclear RNA gene on chromosome 3 (57,512,450 to 57,512,555, forward strand). Ensembl gene ENSG00000206918.
Homologues: Orthologues: chimpanzee U6 (100% identical), mouse Gm25253 (85% identical), rabbit U6 (78% identical), guinea pig U6 (67% identical). Paralogues in human: RNU6-12P (93% identical), RNU6-13P (93% identical), RNU6-16P (93% identical), RNU6-32P (93% identical), RNU6-393P (93% identical), RNU6-41P (93% identical), RNU6-1 (92% identical), RNU6-1060P (92% identical), RNU6-116P (92% identical), RNU6-15P (92% identical), RNU6-17P (92% identical), RNU6-18P (92% identical), and 1286 more.